G6PD (glucose-6-phosphate dehydrogenase)
Diseases named in the same sentence as G6PD in open-access papers (continued):
Sharing a sentence is not in itself a finding about the gene and the disease.
malaria (continued). "Although the data to support efficacy against malaria are limited, this dose has been associated with a limited and clinically apparent haemolytic anaemia in moderately G6PD-deficient subjects, but these findings do not conclusively indicate that non-specific administration of PQ is safe." (PMID 26753754, 2016). "Absent certain knowledge of patient G6PD status, healthcare providers managing patients infected by Plasmodium vivax or Plasmodium ovale malaria must choose between risk of harm caused by hemolytic toxicity of primaquine and that caused by the parasite after withholding therapy." (PMID 26894297, 2016). "In the current study, the performance of the CareStart G6PD (G6PD RDT, AccessBio, USA) device against the FST using quantitative spectrophotometric G6PD assay as diagnostic gold standard was compared among residents in a malaria-endemic area of rural eastern Indonesia." (PMID 26894297, 2016). "Our work demonstrates that studies of severe malaria and G6PD enzymatic function across African populations require, in addition to complete and accurate G6PD phenotypic classification, the identification and analysis of the full repertoire of G6PD genetic markers." (PMID 25671784, 2015). "These polymorphisms explain an additional 4.3% of the variation in risk of severe malaria (and 19.2% of the explainable variation) over and above the combined 7.4% accounted for by the HbAS polymorphism (6.3%), α-thalassemia (0.3%), ABO blood group (0.3%), and G6PD (0.5%) genes." (PMID 25805752, 2015). "The lack of a significant difference in the both prevalence and incidence rates of infection among the different G6PD genotypes suggests this mutation might not influence susceptibility to malaria." (PMID 24943486, 2014). "In Afghanistan, as in most of Asia, malaria is caused predominantly by P. vivax but the unknown G6PD status in most patients guarantees that almost none receive adequate drug therapy for radical cure of confirmed vivax malaria." (PMID 23834949, 2013). "Measured G6PD levels may be reduced during acute malaria episodes." (PMID 23537118, 2013). "In addition, the lack of primaquine content poses a safety concern to glucose-6-phosphate dehydrogenase (G6PD) deficient individuals receiving malaria treatment." (PMID 22704709, 2012). "Thus, judged by these parameters, G6PD-deficient malaria patients appeared to be no different from other malaria patients at presentation." (PMID 21849081, 2011). "Of these factors, haemoglobinophathies (HbAS, G6PD- α*) could be the most important in the current study singly or in combination as shown in where 42% of the non-malaria infected children had one or more types of haemoglobinopathies compared to 25% of the non-anemic non-malaria infected children." (PMID 21144084, 2010). "However, in light of its continued widespread use, the risk:benefit of SP with regard to hematological safety in G6PD-normal and -deficient malaria patients needs to be properly investigated versus a non-hemolytic comparator, such as AL." (PMID 19690618, 2009). "This comparison between single-dose tafenoquine after semi-quantitative G6PD screening and 7-day primaquine (with or without G6PD screening) indicates that tafenoquine is a cost-effective option for improving health outcomes for the population at risk of malaria in Brazil." (PMID 40978565, 2025). "This will be used for malaria RDT, blood film microscopy, quantification of parasite density, dengue NS1 screening and G6PD testing." (PMID 38424577, 2024). "In 2019, the WHO Genomics Initiative identified the revision of the WHO G6PD classification scheme as a priority, and the WHO Global Malaria Programme convened a technical consultation panel in January 2022 for this specific purpose." (PMID 39070600, 2024).
malaria (continued). "Three to 5 ml of EDTA-anticoagulated venous blood sample will be collected on screening (Day − 1) for malaria RDT & microscopy, G6PD testing (UV and Biosensor), dengue NS1 RDT and on enrolment (Day 0) for CBC including Hb estimation, and liver function tests." (PMID 38424577, 2024). "This study shows the feasibility of using G6PD tests, both HCP and patient experiences, and demonstrates the associated costs of and changes to health system training and supervision systems that may be required to successfully integrate point of care G6PD testing into malaria case management." (PMID 37242359, 2023). "The effect of co-treatment of malaria with aqueous extract of Ocimum gratissimum leaves (AEOGL) and primaquine on G6PD activity, antioxidant indices and hematological parameters in Plasmodium berghei-infected mice was investigated." (PMID 36399959, 2022). "This study aimed to characterize G6PD and CYP2D6 genetic variations in vivax malaria patients from Yala province, a malaria-endemic area along the Thai–Malaysian border, and determine the biochemical properties of identified G6PD variants." (PMID 36508454, 2022). "In summary, the presence of G6PD MahidolG487A and PKLRR41Q was found in malaria patients in the Southeast Asia with MAFs of 7.1% and 2.5%, respectively." (PMID 36038921, 2022). "Many (60.9%) complained about the low sensitivity of the malaria RDT and were resistant to the idea of using it again, even for a different purpose (detection of G6PD levels)." (PMID 34003840, 2021). "Little is known how malaria affects glucose-6-phosphate dehydrogenase (G6PD) activity and whether changes in activity when patients present may lead qualitative tests, like the fluorescent spot test (FST), to misdiagnose G6PD deficient (G6PDd) patients as G6PD normal (G6PDn)." (PMID 34495956, 2021). "On 1632 blood samples from soldiers who were admitted to recruitment training camps in a malaria-endemic region, a POC G6PD activity test using the CareStart G6PD & Hb kit was performed." (PMID 32873296, 2020). "However, when G6PD status cannot be reliably retained (e.g., in migratory populations) or requires confirmatory testing (i.e., initial test during an acute illness), repeated G6PD testing will reduce the cost-effectiveness of any health-related program, such as malaria elimination." (PMID 32766454, 2020). "Given available evidence that suggests splenomegaly may be associated with malaria, including P. vivax and P. ovale, in this cohort and from prior investigations, clinicians should administer primaquine to all eligible G6PD-negative patients with suspected tropical splenomegaly." (PMID 32372751, 2020). "There are extensive reports in the literature regarding selection pressure driven by malaria in the HBB, ABO, DARC and G6PD genes." (PMID 30849090, 2019). "This prevalence is thought to be related to the selective advantages against malaria of both SCD and G6PD gene as they provide some sort of immunity against malaria parasites especially, plasmodium falciparum." (PMID 31016042, 2019). "This highlights the importance of knowing the host G6PD and CYP2D6 activities for effective radical cure of relapsing malaria by primaquine." (PMID 31399061, 2019). "Interestingly, when the studies were grouped according to the continents where the studies were performed, we observed that the negative association between G6PD and malaria was only observed for studies performed in Africa (OR, 0.59; 95% CI, 0.40–0.86; n, 11; P = 0.007)." (PMID 28382932, 2017). "Also, the presence of other factors that could protect from malaria, especially hemoglobinopathies like sickle cell anemia (HbS) which also overlaps with G6PD and malaria endemicity, is considered one of the major confounders of our analysis and limitations of this study." (PMID 28382932, 2017).
malaria (continued). "This study affirms the good diagnostic performance of a new qualitative G6PD screening device, the G6PD RDT, intended for use at the point-of-care typical of where most malaria patients live." (PMID 26894297, 2016). "An evaluation of the suitability of the G6PD RDT should be done employing the intended end-users, i.e., paramedics or specially trained residents who today conduct malaria RDT diagnostics and dispense antimalarial therapy at the village level." (PMID 26894297, 2016). "Due to intensification of malaria control programmes worldwide and the perspectives for malaria elimination in some regions where PQ could be massively deployed, it is important to better characterize prevalence of G6PD in malaria endemic communities in these areas." (PMID 27225440, 2016). "It would be followed by primaquine treatment as per WHO recommendations, with the need for prior glucose-6-phosphate dehydrogenase (G6PD) testing determined by the dosing strategy used, to eradicate gametocytes of the potentially resistant malaria strain." (PMID 25942008, 2015). "Although there had been a few studies described in the past in Sri Lanka on G6PD enzyme functional deficiency, there are no studies, as far as it is known to identify genetic polymorphisms and nucleotide variability of the G6PD gene and no information exists on its association with malaria." (PMID 25885177, 2015). "Blood samples for G6PD fluorescent spot test (FST), G6PD genotyping, and malaria testing were taken from 504 unrelated males of Karen and Burman ethnicities presenting to the outpatient clinics." (PMID 25536053, 2014). "As demonstrated by this study, G6PD screening using the WST8 assay can be easily nested into other public health interventions, which is advantageous for its inclusion in malaria elimination programmes contemplating the use of primaquine." (PMID 23782846, 2013). "Many other genes, such as glucose-6-phosphate dehydrogenase (G6PD), ABO, and human leukocyte antigen, are also believed to be evolutionarily interacted with malaria." (PMID 23497175, 2013). "It is significant that malaria resistance genes are often extremely variable, for example, the malaria resistance genes ABO, G6PD, HLA, α-globin, and β-globin, are some of the most variable human genes." (PMID 23088866, 2012). "This was acknowledged through CONITEC's recent recommendation that tafenoquine following semi-quantitative G6PD screening be incorporated into the SUS, an essential milestone with Brazil becoming the first malaria-endemic country to introduce tafenoquine into its health system." (PMID 40978565, 2025). "Further analysis of blood G6PD activity revealed that individuals without Plasmodium infection had lower peripheral blood G6PD activity compared to malaria patients." (PMID 40993672, 2025). "In the absence of routine G6PD testing, many malaria-endemic countries have adopted conservative treatment strategies, using low-dose primaquine (0.25 mg/kg daily for 14 days) to minimize the risk of drug-induced haemolysis." (PMID 41219866, 2025). "These analyses included participants who tested negative for malaria and were afebrile at the time of G6PD testing, aiming to avoid enzymatic activity modulation by acute infections." (PMID 41433239, 2025). "HCPs attributed their errors in conducting the G6PD to the few practical classes they received, lack of practice because of a decline in malaria cases shortly after implementation, a change in routine, and unfamiliar procedures." (PMID 38837977, 2024). "This is explained by the absence of patients with more than one G6PD assays result before 2018 and the drastic decrease in malaria cases in our territory since 2020." (PMID 38725027, 2024). "In areas where G6PD testing is not available, most malaria-endemic countries adopt a primaquine regimen at a lower dose (ie, 3·5 mg/kg total dose) administered during 7 days or 14 days." (PMID 37748497, 2024).
malaria (continued). "Currently available drug regimens including primaquine and tafenoquine, which target hypnozoites, are not safe for patients who are deficient in glucose-6-phosphate dehydrogenase (G6PD), many of whom live in malaria-endemic areas." (PMID 39639330, 2024). "Interviews noted that VHVs expressed hesitancy in interpreting the G6PD test results because they have not historically conducted malaria-related tasks, particularly blood drawing and medicine dispensation." (PMID 37438774, 2023). "Among G6PD normal males, the median G6PD activity was significantly lower for P. vivax positive males compared to malaria negative males at the Kolkata, India, site, but not at the Porto Velho, Brazil, site." (PMID 37824592, 2023). "In addressing the diagnostic challenges and gender disparity issues by the currently available qualitative POC method, particularly for radical malaria elimination, the latest technological innovation of POC devices was developed to quantitatively measure G6PD enzyme activity." (PMID 37388931, 2023). "Based on the findings from this study, we conclude that SCT, α-thalassemia, G6PD mutations, and in-utero exposure to MSP-2 do not influence EBV susceptibility in infants from the malaria holoendemic region of Western Kenya." (PMID 37340364, 2023). "Mean difference of haemoglobin in G6PDd/G6PD normal (G6PDn) patients was − 0.16 g/dL (95% CI − 0.48, 0.15; I2 5%, p = 0.39), regardless of the type of malaria and dose of drugs." (PMID 36872344, 2023). "The card was seen as a document that showed the patient’s history of malaria, to know when and what type of malaria he/she had within a certain period, while the G6PD result section received little or no attention." (PMID 36422580, 2022). "Whilst the overall mean G6PD activity in Ethiopian participants was 4% higher during follow up compared to during the malaria episode, this modest rise was not clinically relevant." (PMID 35544453, 2022). "Recently, in the absence of reliable G6PD tests beyond the hospital level, the malaria program in Laos has rolled out the primaquine 8 weeks regimen up to the health center level." (PMID 35468145, 2022). "R: At that time if a patient came for testing with malaria, and after the test result positive, I gave him 1 dose of AMQ [antimalarial therapy, artesunate/mefloquine] then I sent him to health centre to check G6PD with machine." (PMID 36195916, 2022). "Because G6PD testing was not usually available at the point of care in malaria endemic regions, this limited the use of primaquine with some countries choosing to add it and some not." (PMID 36191877, 2022). "This study revealed that malaria patients with G6PD MahidolG487A, but not with PKLRR41Q, had anaemia during infection." (PMID 36038921, 2022). "Many studies show the G6PD c.202G > A and c.376A > G variants and Duffy-negative blood group are two RBC variants that confer protection against malaria." (PMID 35527254, 2022). "Two male participants reported signs and symptoms of hemolysis, such as dark urine and jaundice; one had a normal G6PD result while the other had no information on G6PD activity in the malaria form." (PMID 36422580, 2022). "The observation that G6PD activity increases during acute malaria is not unexpected, however the degree to which this occurred in our study was surprising with potentially important public health implications." (PMID 35544453, 2022). "All consenting and eligible household members and members of households within a 100-m radius will be treated without RDT testing for malaria with AL plus 14 days of PQ after receiving G6PD testing and only those with G6PD value ≥4 U/Hgb will be given PQ." (PMID 35392979, 2022). "R: No... because we tested for malaria and the same time, we tested for G6PD [with the same sample]." (PMID 36195916, 2022).
malaria (continued). "Since only patients initially presenting with malaria were enrolled and there were no aparasitemic controls, one cannot definitively infer that initial elevations in G6PD activity were attributable to the initial peripheral parasitaemia." (PMID 35544453, 2022). "Conversely 287 out of 290 individuals categorized as G6PD normal during follow up had no change in G6PD status when presenting with malaria." (PMID 35544453, 2022). "Recently the WHO recommended a 0.25 mg/kg single-dose primaquine to be added to ACTs for the elimination of malaria in low-transmission settings and in settings threatened by artemisinin resistance without the need for screening of G6PD status." (PMID 35216617, 2022). "Should G6PD testing and radical cure with shorter course regimens be centralized with qualified LTs and doctors at UHC and DH level, or rather be done at community level and in remote areas, closer to the malaria patients?" (PMID 33980257, 2021). "Of the 11 males with G6PD activity levels within intermediate ranges (30 to 70%) according to the reference test, none were malaria positive." (PMID 34383774, 2021). "Although the need for G6PD testing before primaquine administration has been recognized, the health system in Sudan does not currently integrate G6PD testing into the malaria control program." (PMID 34699526, 2021). "The filter parameters are the number of records (positive or negative tests), the G6PD status, the malaria type, the treatment and the parasitaemia (parasites/mm3)." (PMID 34717641, 2021). "Assuming the reliability of G6PD biosensor measurement, the possibility to administer primaquine to patients on the basis of G6PD activity was simulated and assessed (note: the patients included in the present study were not malaria-infected)." (PMID 34353361, 2021). "Some point-of-care quantitative G6PD tests have now been validated in laboratory settings but field validation for use in malaria case management has not yet been completed." (PMID 31969155, 2020). "The effect of genetic variation at G6PD on infectious diseases other than malaria has not been widely studied." (PMID 32536341, 2020). "While not statistically significant, the median G6PD activity was almost 25% higher (1.7U/gHb) among patients with malaria diagnosed by microscopy or RDT compared to participants with a negative result." (PMID 32925910, 2020). "Improving care and prevention of malaria in pregnancy, reducing unnecessary exclusion of women from radical cure, and providing quantitative G6PD screening that is as accurate for females as it is for males are achievable steps towards the SDG for a more equitable and malaria-free world." (PMID 31969155, 2020). "Safety, tolerability, CYP2D6 and G6PD variant data from this study support the deployment of the WHO-recommended SLD primaquine without G6PD testing to advance malaria elimination in South African districts with low-intensity residual transmission." (PMID 31234865, 2019). "However, in order not to overlook anyone and ensure a safe primaquine therapy for people living in malaria endemic areas in Lao PDR, G6PD testing is necessary." (PMID 30866940, 2019). "Our study is the first to systematically investigate the safety of SLD-PQ at doses of ≥0.40 mg/kg in G6PD-d individuals without malaria, addressing the evidence gap identified by the WHO Expert Review Group that issued the recommendation to use SLD-PQ." (PMID 29342267, 2018). "For G6PD genotyping, G6PD B was detected in 87.5% and A376G detected in 12.5% of malaria patients, whereas G202A and C563T were absent." (PMID 30918572, 2018). "Since G6PD testing is not widely available, doctors often avoid prescribing primaquine to treat malaria, which results in more cases of disease relapse." (PMID 28155819, 2017). "A lack of G6PD leads to a lack of reducing equivalents, an increase in oxidative stress and, thus, to host protection against severe malaria." (PMID 28874682, 2017).